ERCC1 (ERCC excision repair 1, endonuclease non-catalytic subunit)
Diseases named in the same sentence as ERCC1 in open-access papers (continued):
Sharing a sentence is not in itself a finding about the gene and the disease.
tumor (continued). "However, a strong correlation was observed between the mRNA expression levels of APTX and BRCA1 (rho = 0.53, P < 0.001), APTX and ERCC1 (rho = 0.73, P < 0.001), BRCA1 and ERCC1 (rho = 0.48, P < 0.001) in tumor." (PMID 23517622, 2013). "Two genes remained significant in variant of a multivariate model that did not account for tumor stage: ERCC1 (RR = 0.53, 95% CI 0.30–0.96, p = 0.03) and CA9 (RR = 1.79, 95% CI 1.00–3.21, p = 0.05)." (PMID 22848476, 2012). "All ERCC1 scores were next computed against the tumor categories (part C and D)." (PMID 21961533, 2011). "In this context, we assume that pre-therapeutic ERCC1 protein levels within tumor cells might be correlated with their cisplatin-related DNA damage repair capacity." (PMID 21426588, 2011). "The lower likelihood of response to platinum-based chemotherapy in high ERCC1 expressing tumours observed further supports the notion that ERCC1 might be predictive of lack of platinum benefit." (PMID 22022380, 2011). "A number of tumour biomarkers have been investigated for prognostic and predictive utility when considering systemic therapy, and prominent amongst these is excision repair cross-complementation group 1 (ERCC1) protein." (PMID 22022380, 2011). "Importantly, many tumor cell clusters were heavily admixed with inflammatory cells also expressing ERCC1 with intensity score 2-3." (PMID 21961533, 2011). "Meta-analysis of three studies in SCLC (292 patients), also provided evidence of a trend towards increased response to platinum-containing chemotherapy in high ERCC1 expressing tumours (average RR = 1.14; 95% CI: 0.99–1.31, p = 0.08; I2 = 0%), although this was not statistically significant." (PMID 22022380, 2011). "This is clinically important as it demonstrates that ERCC1-XPF could be used as a target to enhance the response of tumours to ICL-inducing drugs." (PMID 20846399, 2010). "ERCC1 expression levels, measured by assessing messenger RNA (mRNA) or protein levels in tumor cells, may have both prognostic and predictive value to NSCLC patients." (PMID 21152077, 2010). "A phase III trial investigated whether selecting patients for cisplatin treatment based on pretreatment ERCC1 levels in tumor specimens improved patient outcomes." (PMID 21152077, 2010). "The ERCC1 protein was expressed in 27 out of 33 tumor samples (82%)." (PMID 20066159, 2009). "Expression of the excision repair cross-complementing gene 1 (ERCC1) may play a role in human tumours because it is essential for nucleotide excision repair and influences genomic instability." (PMID 19259093, 2009). "In contrast, in a study of non-small-cell lung cancer (NSCLC), the median H score for ERCC1 expression was 1.0 and 30–40% of tumours expressed ERCC1, suggesting that the proportion and pattern of ERCC1 expression varies according to the tumour type." (PMID 18594541, 2008). "The authors hypothesized that patients receiving therapy according to their baseline tumor ERCC1 mRNA levels would achieve higher response rates and more prolonged survival than patients in the control arm receiving non-customized therapy." (PMID 19578506, 2008). "Thirty-three (73%) tumours with H score ⩾2.0 were defined as having high expression of ERCC1." (PMID 18594541, 2008). "The predictive role of pretreatment ERCC1 expression level might be connected with the capacity for DNA damage repair, that is, tumour cells with a more efficient DNA repair capacity can be resistant to cisplatin-based chemotherapy or radiotherapy." (PMID 18594541, 2008). "We found a high expression of ERCC1 in 73% of SCCHN tumours." (PMID 18594541, 2008). "The purpose of this study was to evaluate whether the immunohistochemical expression status of ERCC1 can predict the tumour response and cancer-specific survival in patients with locally advanced SCCHN being treated with cisplatin-based CCRT." (PMID 18594541, 2008).
tumor (continued). "One of the molecular explanations for the supra-additive effects on tumour growth presently observed may lie in the changes in tumour expression of the DNA repair protein ERCC1." (PMID 17592499, 2007). "Therefore, the expression and function of DPYD, TYMS, MTHFR, ERCC1, ERCC2, XRCC1, and GSTP1 may be influenced not only by genetic polymorphisms, but also by processes that are specific for the tumor tissue." (PMID 33429840, 2021). "Two frequent ERCC1 SNPs have been hypothesized to represent tumor activity." (PMID 34898581, 2021). "This analysis revealed that the XP-C tumor mutational profiles and their NMF-derived mutational Signature “C” had the highest similarity to the COSMIC Signature 8 (cosine similarity of 0.87−0.92, and 0.86 respectively) and formed a cluster together with XPC and Ercc1 organoid knockouts." (PMID 33203900, 2020). "Based on these data, we hypothesize that NSCLC patients with a tumor positive for ERCC-1 gene SNPs could be more genetically instable, could present higher mutational load, and consequently could be more responsive to PD-1 ICB when compared to subjects negative for these genetic alterations." (PMID 32983959, 2020). "As shown in, low nuclear ERCC1 level was significantly associated with aggressive phenotypes, including high grade, no special histological type (NST), ER−, basal-like phenotype and triple negative tumours, as well as loss of other DNA repair biomarkers (all adjusted p ≤ 0.01)." (PMID 31405143, 2019). "PARP inhibitor selectively triggers anti-tumor immunity in ERCC1- or BRCA-defective contexts, indicating that PARP inhibitors might promote therapeutic effects by inhibiting DNA damage repair and activating anti-tumor effect in populations with DNA repair defect." (PMID 32010626, 2019). "Therefore, it is reasonable to hypothesize that changes in expression of ERCC1 levels in PMBC can be used as a surrogate to tumor tissue." (PMID 31565185, 2019). "Moreover, recent data indicated that ERCC1 silencing by RNA interference may provide a means to potentiate cisplatin-induced tumor cell killing." (PMID 30208165, 2018). "However, in patients with low-medium Ki67 and high ERCC1 levels, although there is a certain degree of resistance to chemoradiotherapy, the risk of proliferation for the tumor itself is not high, which can yield relatively better prognosis." (PMID 29179456, 2017). "Thus, we explored whether ERCC1 status predicted tumor response and survival in patients with metastatic or recurrent uterine cervical cancer receiving platinum-based chemotherapy." (PMID 29390553, 2017). "To evaluate the expression levels of ERCC1 in tumor cells, where the observed staining intensity may be affected by pre-analytical and analytical factors, we sought to identify relevant tissues that express the protein, so that these tissues could be used as an external reference." (PMID 24603753, 2014). "Furthermore, we hypothesized that even a minor component of tumor cells with high ERCC1 expression may form the basis for tumor recurrence following oxaliplatin-based chemotherapy." (PMID 24603753, 2014). "Tumor samples obtained by fiberoptic bronchoscopy and computerized tomography-guided needle biopsy were analyzed by immunohistochemistry for intratumoral level of excision repair cross-complementing gene 1 (ERCC1), ribonucleotide reductase M1 (RRM1), and β-tubulin III." (PMID 25119181, 2014). "Also, our results do not support semi-quantitative association between tumor ERCC1 nuclear protein expression and clinical and pathological outcomes in the patient cohort in this study." (PMID 25191856, 2014).
tumor (continued). "In the present study, we retrospectively investigated whether the clinicopathologic factors and the expression levels of ERCC1 in tumor tissue, measured using immunohistochemical staining, were associated with prognosis in Chinese patients who underwent surgery for p-stage III-N2 NSCLC." (PMID 23759026, 2013). "This correlation between ERCC1 or BRCA1 expression and CRC metastasis has been suggested recently, but no statistical association could be established between reduced expression of ERCC1 or BRCA1 and tumor stage and lymph node involvement." (PMID 23496813, 2013). "Nevertheless, other than previously reported, we did not observe an association between tumor excision repair gene polymorphisms and patient outcome, possibly due to the small sample size, while the investigated polymorphism in ERCC1 was not related to the corresponding mRNA and protein expression." (PMID 20066159, 2009). "mRNA expression analysis and single nucleotide polymorphism (SNP) characterization of three NER pathway genes—namely ERCC1, ERCC2, and ERCC5—were performed on patient tumor samples." (PMID 39735668, 2025). "The overexpressions of ERCC1 and ACTL6A were found to significantly enhance the infiltration of CD8+ T-cells, macrophages, dendritic cells, CD4+ T-cells, and B-cells into HNC tumor cells." (PMID 40510426, 2025). "The higher gene expression of ERCC1, ERCC2, and ERCC5 in tumor samples compared to healthy control is consistent with previous studies that reported high tumor tissue levels of NER pathways genes, mainly ERCC1, in SCLC and in other solid tumors." (PMID 39735668, 2025). "We analyzed polymorphisms in genes related to PE chemotherapy and radiotherapy in germline DNA, and evaluated the expression of ERCC1 and ERCC1-XPF proteins in tumor tissue." (PMID 39339159, 2024). "Surprisingly, an increase in ERCC GSVA scores displayed a positive tendency toward the activation of the cell apoptosis pathway, which is contradictory to experimental evidence that inhibition of ERCC1, ERCC6L, or ERCC8 promotes apoptosis of tumor cells." (PMID 39582530, 2024). "The multivariable analysis further underscored the significance of age, ABCC3, ERCC1, RFC1, and specific tumour histologies in predicting treatment outcomes." (PMID 39335211, 2024). "When the tumor volume grew to 50 mm3, PBS, 2 mg/kg of 5-FU, 2 mg/kg of the ERCC1–XPF blocker, and a combination of 2 mg/kg of 5-FU with 2 mg/kg of the ERCC1–XPF blocker was administered." (PMID 37296596, 2023). "Defects or inhibition of ERCC1-XPF can affect the function of the NER, reducing the ability of tumor cells to effectively repair cisplatin-induced DNA damage and thus increasing tumor cell mortality." (PMID 37305685, 2023). "Interfering with EEF1D gene expression in mice xenografted tumor significantly affected the levels of OPTN, p-Akt, Bcl-2, Bax, cleaved caspase-3 and ERCC1 compared to DDP treated mice alone, and had less effect on PI3K, Akt and caspase-3." (PMID 35672728, 2022). "For example, high expression levels of ERCC1 and BRCA1, which are crucial for DNA repair, negatively affect the efficacy of platinum drugs and are thought to be a major predictor of tumor responses to platinum-based chemotherapy." (PMID 36294786, 2022). "The largest regulatory network they found included ERCC1, PARP, Snail, c-Met, Caspase-8, and Rb, but connections to RB were reduced in a subgroup that showed tumor progression." (PMID 35672443, 2022). "In this way, it was demonstrated that ECGC is a potent inhibitor of ERCC1-XPF activity, which leads to sensitization of tumor cells to CDDP, thus increasing cell death and reducing proliferation." (PMID 35669542, 2022). "On the basis of experimental research, this study detected molecular markers (ERCC1, RRM1, and TUBB3 mRNAs) in tumour tissue specimens from patients who needed adjuvant chemotherapy after surgery." (PMID 34603450, 2021).
tumor (continued). "In this study, a prospective randomized controlled trial was conducted to measure the molecular markers (mRNA expression of ERCC1, RRM1, and TUBB3) in tumour tissue specimens from patients who needed adjuvant chemotherapy after surgery." (PMID 34603450, 2021). "In the SG-resistant, BRCA1/2-wildtype MDA-MB-231 TNBC tumor line, several HRR proteins were found to be upregulated upon SG exposure, among them ERCC1 and Rad51." (PMID 33196706, 2020). "The hypothesis that a single complex (ERCC1/XPF) and/or DNA pol β could be associated with platinum response can be viewed as simplistic and other factors (i.e., HR proficiency, tumor heterogeneity) could play a more important role in platinum sensitivity/resistance." (PMID 32847049, 2020). "Gene expression analysis of 4 genes (BRCA1, CUL4A, ERCC1, and ERCC5), involved in the DNA damage repair (DDR) machinery, was performed in 66 surgical tumor samples." (PMID 32365979, 2020). "However, the prevalence of ERCC1 promoter methylation in other tumor types is unknown." (PMID 33291532, 2020). "High ERCC1 expression was found in 47.3% patients, and was correlated with higher TNM (p = 0.021), tumor enlargement (p = 0.002), positive lymph nodes (p = 0.001), positive distant metastasis (p = 0.005), and higher relative risk of death (p < 0.001)." (PMID 31521181, 2019). "We then compared proteomic results and found higher frequencies (false-discovery rate-adjusted q-value < 0.05, logistic regression) in ERCC1, TOP1 and MET protein expression in metastatic lesions compared with primary tumours." (PMID 31292535, 2019). "Statistically significant differences in overall survival were found according to ECOG (p < 0.001), tumor size (p < 0.001), lymph nodes (p < 0.001), distant metastasis (p < 0.001), TNM (p = 0.01), and ERCC1 expression (p < 0.001)." (PMID 31521181, 2019). "The most common tumor molecular profile was low RRM1 and ERCC1 (44.4%), and these patients were treated with a doublet of gemcitabine and oxaliplatin." (PMID 31065624, 2019). "High ERCC1 expression was found in 61 (47.3%) patients and was strongly correlated with higher TMN (p = 0.021), tumor enlargement (p = 0.002), positive lymph nodes (p = 0.001), distant metastasis (p = 0.005)." (PMID 31521181, 2019). "This current study presents a large dataset exploring a role for tumor MMR status and ERCC1 expression with respect to prevalence of CRC and disease outcome in a population of chinese patients (n = 2233)." (PMID 28767665, 2017). "BZA treatment also significantly reversed chemo and radioresistance in tumor cells by downregulating XRCC-1, ERCC-1 and survivin." (PMID 28978005, 2017). "Scenario 3 included ERCC1 expression, pre-operative PSA, clinical tumor stage (cT stage) and Gleason grade obtained on the prostatectomy specimen." (PMID 28747165, 2017). "The median value of AEG-1 H-score was 120 (range 0–255) and, as in the case of TS and ERCC1, it was used to divide patients into those who had either high or low AEG-1 expression level in tumor tissues." (PMID 28977913, 2017). "Excessive HSA significantly up-regulated the protein expression of ERCC1 and TOP2A respectively in mice with tumor." (PMID 27895586, 2016). "In the same hospital, significantly different expressions between matched tumour and healthy adjacent tissues were observed for 6 genes (APEX1, DDB1, ERCC1, NEIL1, PARP1, RPA2) after snap freezing collection." (PMID 27383461, 2016).
tumor (continued). "Although RRM1 and ERCC1 can be potential biomarkers for resistance to chemotherapeutic agents and patient prognosis, data to correlate RRM1 and ERCC1 status with tumor response to gemcitabine plus platinum in advanced UC are lacking." (PMID 26200905, 2015). "Kaplan-Meier analysis showed a trend in shorter OS for patients with RRM2, TS, and ERCC1, BRCA1 overexpressed tumours." (PMID 26663950, 2015). "The expression of ERCC1 and β-tubulin III were analysed by immunofluorescence staining in isolated tumor cells from ascites (control) and its paclitaxel-treated (6 ng/ml for 3 days) counterpart." (PMID 24886434, 2014). "These two preparations contained similar amounts of tumor cells, had similar reactivity to RRM1 and ERCC1, and similar resistance to the tested drugs." (PMID 25253633, 2014). "Through correlation analysis of RRM1, ERCC1, and BRCA1 mRNA expression levels, our results indicated a linear correlation between peripheral blood and tumor tissue RRM1 expression." (PMID 24591771, 2014). "Nonetheless, in these two trials, the number of considered genes was limited to ERCC1 or both ERCC1 and RRM1 that seem unlikely representing an extensive view of the biological tumor heterogeneous behavior." (PMID 25674536, 2014). "Irinotecan treatment results in the accumulation of DNA strand breaks in tumor cells, and APTX, BRCA1 and ERCC1 have been shown to have important roles in the repair of DNA single- and double-strand breaks." (PMID 23517622, 2013). "Univariate analysis showed that tumor stage and tumor location were important factors affecting the OS and PFS, though ERCC1 expression and betel nuts chewing were the prognostic factors in OS by multivariate analysis according to Cox regression model." (PMID 21426588, 2011). "Regarding four commonly studied polymorphic sites in ERCC1, ERCC2/XPD, and XRCC1, it was interesting to identify discordant tumor tissue/peripheral blood genotypes." (PMID 20066159, 2009). "Their results suggest that ERCC1 and RRM1 expression evaluated by real-time RT-PCR are predictors of tumor response in patients treated with the gemcitabine-platinum doublet regimen." (PMID 19578506, 2008). "We measured mRNA level of ERCC1 and BRCA1 in tumor cells isolated from malignant effusions and correlated them with cisplatin and/or docetaxel chemosensitivity in vitro." (PMID 18402708, 2008). "A prospective, phase II clinical trial that used tumor expression of RRM1 and ERCC1 mRNA as detected by real-time quantitative polymerase chain reaction (RT-QPCR) for selection of chemotherapy in advanced NSCLC patients has been recently conducted." (PMID 19452042, 2008). "Thus, we can predict that both ERCC1 and ACTL6A are upregulated in HNC patients, particularly in individuals with advanced stages and tumor grades and mostly in persons aged 40–80 years." (PMID 40510426, 2025). "Low ERCC1 expression in tumor tissue has been correlated with better survival in non-small-cell lung cancer (NSCLC) and in SCLC patients treated with platinum-based chemotherapy." (PMID 39339159, 2024). "In total, 11 of 106 FFPE tissues samples were not evaluable for ERCC1 protein expression due to insufficient representative tumor tissue." (PMID 39339159, 2024). "ABCB1, ABCC1\2\3, ABCG2, ERCC1, XRCC1\2 can induce tumor chemo-resistance and radio-resistance." (PMID 37283789, 2023).